IL1B (interleukin 1 beta)
Diseases named in the same sentence as IL1B in open-access papers (continued):
Sharing a sentence is not in itself a finding about the gene and the disease.
colitis (continued). "Specifically, the levels of TNF-α, IL-1β, IL-6, IL-10, IL-2, and IL-12 SOD, CAT, GSH-Px, and MDA were modulated in rats with colitis, also inhibiting TLR4/NF-κB pathway activation." (PMID 39494333, 2024). "A previous study using a colitis animal model has shown that exercise reduces pro-inflammatory cytokines TNF-α and IL-1β expression, increases anti-inflammatory cytokine IL-10 expression, and reduces stress-induced barrier dysfunction." (PMID 38791116, 2024). "The concentrations of proinflammatory cytokines IL-6, IL-1β, and TNF-α significantly increased in the serum of mice with colitis induced with DSS, while the concentration of immunoglobulin IgA in serum was decreased in the DSS group." (PMID 38398846, 2024). "S. cerevisiae strains exhibited in vivo reduction of pro-inflammatory cytokines IL-1β, IL-6 and TNF-α and promoted the expression of the anti-inflammatory cytokine IL-10 in colitis mice." (PMID 39628717, 2024). "The improvement of colitis after hesperidin treatment is related to the inhibition of pro-inflammatory cytokines TNF-α, IL-6, IL-1β, and IL-33 as well as NF-κB activation in the colon." (PMID 39494333, 2024). "Increased levels of crucial proinflammatory cytokines, such as IL-6 and IL-1β, were evident in a translational model of DSS-induced colitis in BALB/c mice." (PMID 37695333, 2024). "In the current DSS-induced colitis model, we found that LRRK2 G2019S promotes inflammasome activation, resulting in elevated production of IL-1β and IL-18 in the gut epithelium." (PMID 38607004, 2024). "The positive association of glycine with IL10 also aligns well with a previous study, wherein glycine exhibited anti-inflammatory effects by reducing colonic expression of IL1β and promoting IL10 cytokines in a colitis mouse model." (PMID 38352704, 2024). "Strains that induced higher levels of the anti-inflammatory cytokine IL-10 and lower levels of pro-inflammatory cytokines such as IL-1β, IL-6, interferon γ (IFNγ), and TNF-α offered protection in induced colitis." (PMID 39767038, 2024). "In the colitis mice, the expression of IL-6, TNF-α, and IL-1β in the colon tissue was significantly increased after treatment with HPAD or HSAD." (PMID 38233383, 2024). "Bifidobacterium adolescentis ameliorated DSS-induced colitis by reducing TNF-α, IL-1β, and IL-6 levels and increasing IL-10 and IL-4 levels." (PMID 38540864, 2024). "Butyrate acid and propanoic acid, key components of XYKJP, play a crucial role in reducing colonic mucosal injury and decreasing IL-1β, TNF-α, and IL-6 in the colitis mouse model." (PMID 39133435, 2024). "For example, L-fucose inhibits macrophage M1 polarization, inactivates the NLRP3 inflammasome, and decreases the levels of TNF-α, IL-1β, and IL-6 in mice with DSS-induced colitis." (PMID 38596683, 2024). "L. plantarum HNU082 and B. adolescentis also attenuated the inflammatory response in a DSS-induced colitis by downregulating TNF-α and IL-1β while upregulating IL-10." (PMID 37639209, 2024). "Significantly higher levels of IL-6, IL-1β and TNF-α were detected in mice with colitis compared to control mice." (PMID 39165355, 2024). "Similar to the reported effects of MSCs in chemically-induced colitis, BM-MSC treatments in Winnie mice downregulated the expression of Il6, Ifng, Il1b, Il1a, Tnf, Cxcl2, Tbx21 and Itgam, which were upregulated in Winnie mice and IBD patients." (PMID 38503815, 2024). "In models of colitis, Hericium erinaceus has shown significant downregulation of TNF-α, alongside reductions in IL-6 and IL-1β, reflecting its role in mitigating inflammation similarly to EPA and GLA combinations." (PMID 39597805, 2024). "An earlier experiment demonstrated that L. rhamnosus GG Effector Protein HM0539 substantially mitigated inflammation and downregulated IL-6, IL-1β, and TNF-α in murine colitis." (PMID 37639209, 2024).
colitis (continued). "Here, in the zebrafish colitis model, DSF treatment significantly inhibited the abnormal increase in the expression of pro-inflammatory cytokines (tnfa, il1b, and il6) and the decrease in the expression of the anti-inflammatory factor il10." (PMID 38892496, 2024). "ELISA results indicated that DSS-induced colitis mice administered with PSPRS showed higher IL-10 and IgA levels but lower TNF-α, IL-1β, and IL-6 levels." (PMID 38611336, 2024). "Compared to the control group, the expression levels of the TNF-α (p < 0.001), IL-1β (p < 0.001), and IL-6 (p < 0.05) genes were significantly increased in the DSS-induced colitis group." (PMID 38474831, 2024). "SASP can reduce oxidative stress and the inflammatory response in TNBS-induced colitis model rats by reducing the expression of TNF-α and IL-1β and inhibiting IL-6/JAK2/STAT3 signal transduction." (PMID 39318778, 2024). "Another study has shown that Gal-3 inhibitor DAVANAT® reduces cholangitis induced by Novosphingobium aromaticivorans and DSS-induced colitis by reducing the activation of NLRP3 inflammasome and expression of IL-1β in macrophages." (PMID 39125698, 2024). "At the same time, STAT3 knockout also reduced the differences in the expression of IL-6, TNF-α, and IL-1β, as well as ZO-1, occludin, BCL-2, and BAX in the colons of mice with colitis induced by different diets." (PMID 38233383, 2024). "In mouse models of colitis, both walnut protein and its enzymatic products effectively suppressed serum IL-1β, IL-6, TNF-α levels, and myeloperoxidase (MPO) activity, thereby preventing colitis progression." (PMID 39203780, 2024). "extract combined with L. brevis inhibited TNF-α, IL-1β and IFN-γ production in the lymph nodes and spleens of 4% DSS-induced colitis mice." (PMID 36986118, 2023). "Mice treated with SCH experienced significant weight gain, effectively alleviating the severity of colitis, and decreasing the levels of inflammatory factors such as TNF-α, IL-1β, IL-18, IL-6, and other related proteins (NLRP3, Caspase-1, SGK1) in UC mice." (PMID 37674245, 2023). "Proinflammatory cytokines play a critical role in DSS-induced colitis injury as significant elevation of TNF-α, IL-1β, and IL-6, at both mRNA and protein levels, was observed by QRT-PCR and ELISA." (PMID 37284442, 2023). "The mechanism is that G-Rd inhibits DSS-induced experimental colitis in mice by promoting the AMPK-ULK1-p62 axis-driven mitochondrial autophagy-mediated NLRP3 inflammasome inactivation and reducing macrophage IL-1β secretion." (PMID 37849728, 2023). "Collectively, these results suggest that DCA exacerbates TNBS-induced colitis by activating GSDMD-dependent pyroptosis and IL-1β secretion." (PMID 37131223, 2023). "SM@siRNP can scavenge 2,2-diphenyl-1-picrylhydrazide radical, inhibit NO and proinflammatory cytokine (IL-1β, IL-6, TNF-α), significantly improved the damage of colonic mucosa in DSS-induced colitis mice." (PMID 37033644, 2023). "We verified this theory by ELISA and found that IL-1β, IL-6, and TNF-α in the colon tissue of DSS-induced colitis mice were significantly increased, showing a strong anti-inflammatory process." (PMID 36832972, 2023). "Terpenoid component bilobalide can inhibit the expression of IL-1β, IL-6, and TNF-α in DSS-mediated colitis." (PMID 37111225, 2023). "As IL-1β, Tnf-α, and Nos2 expression was elevated in ETBF-infected muMT mice compared with ETBF-infected WT mice, the up-regulation of innate immune responses in ETBF-infected muMT mice could contribute to the persistent colitis in B-cell-deficient mice, which needs further study." (PMID 38203534, 2023). "Increased levels of IL-1β, for example, are related to inflammatory responses to DSS-induced colitis." (PMID 36792680, 2023). "To accomplish this, we used DSS-induced colitis, CFA-induced arthritis, and mBSA/IL-1β-induced arthritis mouse models." (PMID 36793721, 2023).
colitis (continued). "On one hand, HEP10 suppressed the production of TNF-α, IL-1β, IL-6, inducible iNOS, and COX-2 in LPS challenged murine macrophage RAW264.7 cells, as well as in colons from DSS-induced colitis mice." (PMID 36771444, 2023). "The colitis-induced rats had substantial improved healing of their colitis that was evidenced by lower colonic expressions of TNF-α, IL-1β, and hypoxia-inducible factor 1-α." (PMID 36814502, 2023). "The main GBE component flavonoids, such as kaempferol and isorhamnetin, have been shown to reduce IL-1β, IL-6, and TNF-α within DSS-induced colitis animal models." (PMID 37111225, 2023). "The levels of IL-1β, TNF-α and IL-6 in the colitis tissues of β6-KO mice were lower than those of WT mice." (PMID 37223685, 2023). "Since more inflammatory cells infiltration and elevated levels of TNF-α, IL-1β, and IL-6 were observed in colonic tissue of DSS-treated mice, we next examined changes of cellular components involved in the colitis with a special focus on macrophages." (PMID 37813835, 2023). "The balance between pro-inflammatory cytokines, including IL-6, IL-1β, and TNF-α, usually plays a crucial pathological role in colitis by mediating inflammatory responses." (PMID 38138587, 2023). "DPA attenuates inflammation in DSS-induced colitis model; modulates pro-inflammatory cytokines (TNF-α, IL-1β, IL-6) and anti-inflammatory cytokine (IL-10); inhibits synthesis of pro-inflammatory eicosanoids (PGE2, LTB4)." (PMID 37868958, 2023). "Both in vitro and in vivo, the colitis increased NF-kB and NF-kB-p65, COX-2, iNOS, IL-1β, IL-6, and TNF-α activity, in addition to decreasing PPARγ expression." (PMID 36677021, 2023). "VAD mice demonstrated severe experimental colitis and increased expression of inflammasome-related proteins (caspase-11, GSDMD, NLRP3, ASC, caspase-1, IL-1β, and IL-18) in the colonic LP." (PMID 37240022, 2023). "A reduction in colonic IL-1β, IFNγ, and mKC levels was observed in the HF-Colitis and HF-CAC groups when compared to the LF-Colitis and LF-CAC groups." (PMID 36768196, 2023). "The results showed that CuET significantly attenuated LPS-induced mRNA levels of TNF-α, IL-1β, and IL-6, consistent with its anti-inflammatory effect on the DSS-induced colitis model." (PMID 37284442, 2023). "In mouse colitis model, MCC950 was demonstrated to act on NLRP3 by inhibiting ASC oligomerization and caspase-1 dependent activation of IL-1β and IL-18, and reducing the levels of pro-inflammatory cytokines." (PMID 37681916, 2023). "Consistently, the protein levels of inflammatory cytokines TNF-α, IFN-γ, IL-1β, and IL-6 in the serum of MKO colitis mice were increased." (PMID 36635421, 2023). "The levels of TNF-α, IL-6, and IL-1β were increased, and that of IL-10 was decreased after DSS exposure in mice with colitis." (PMID 37047694, 2023). "L-theanine also weakly decreased the expression of IL-1β, IL-6, and TNF-α, which are neuroinflammation- and colitis-related biomarkers." (PMID 37299451, 2023). "Following these findings, nanoparticle-mediated overexpression of miR-223 has been developed to attenuate experimental colitis, NLRP3 activation, and IL-1β release." (PMID 37891577, 2023). "APS can also downregulate the expression of NLRP3, caspase-1, and ASC in colon tissue, prevent the activation of the NLRP3 inflammasome, thereby reducing the expression of IL-18 and IL-1β and alleviating DSS-induced colon inflammation." (PMID 37849728, 2023). "PFKFB3 increased IL-1β and TNF-α in intestinal epithelial cells to promote colitis-related colorectal cancer tumorigenesis." (PMID 38098990, 2023). "The pro-inflammatory cytokines such as IL-1β and TNF-α were involved in the inflammatory process in DSS-induced colitis." (PMID 35838945, 2023). "Reduced colitis severity was also reflected in differential tissue mRNA expression: mucosal transcript levels of S100a9, Il1b and Ptgs2 were significantly reduced in DSS-induced colitis when calcineurin inhibitors were applied." (PMID 37358998, 2023).
colitis (continued). "To determine the mechanism by which neutrophils contribute to colitis, we examined the production of inflammatory factors including TNF-α, IL-1β, and IL-6." (PMID 37813835, 2023). "Previously, similar results reported that B. breve CCFM683 reduced colon inflammation by increasing colon length and reducing TNF-α, IL-1β and IL-6 expression in the colons of DSS-induced colitis mice." (PMID 36986118, 2023). "Meanwhile, the secretion of proinflammatory factors IL-1β, IL-6, TNF-α, and PGE2 was enhanced, as well as the levels of anti-inflammatory factor IL-10 were reduced in the serum of colitis rats, which was all reversed by EA treatment." (PMID 36910013, 2023). "As a consequence, BMDA or DMMA administration reduced expression levels of inflammatory cytokines such as IL-1β and TNF-α in LPS-stimulated THP-1 cells in vitro and in tissues from DNBS-induced colitis and collagen-induced arthritis in vivo." (PMID 37153778, 2023). "In fact, it was shown that the pasteurized preparation of A. muciniphila resulted in downregulation of inflammatory cytokines such as TNFα, Interferon-γ (IFNγ), IL-1β, IL-6, IL-8 and IL-33 with a marked improvement in DSS-induced colitis." (PMID 37370812, 2023). "In our previous study, the prototype ITA aggravated DSS-induced colitis and increased the levels of pro-inflammatory cytokines TNF-α, IL-1β, and IL-6 secreted by macrophages in vitro." (PMID 36770726, 2023). "NETs can activate macrophages to release cytokines such as IL-1β, TNF-α, IL-6, induce the activation of platelets and intestinal epithelial cells, promoting colitis and thrombosis." (PMID 37720208, 2023). "In coptisine chloride therapy for colitis, coptisine chloride significant suppresses mRNA expression, releases of pro-inflammatory cytokines (TNF-α, IFN-γ, IL-1β, IL-6, IL-17) and enhances the mRNA expression level of IL-10, an anti-inflammatory cytokine." (PMID 36859380, 2023). "Indirectly, IL-1β induces the production of prostaglandin E2 (PGE2), which has been shown to inhibit mucosal inflammation in mice with DSS-induced colitis." (PMID 37371485, 2023). "Previous studies have demonstrated that the derangement of cytokines drives colitis pathology and disease progression, TNF‐α, IL‐1β, and IL‐6 are important pro‐inflammatory effectors that function in the context of intestinal inflammation." (PMID 37970386, 2023). "The representative secreted cytokines are IL-1β, IL-6, and TNF-α, and these induce systemic pro-inflammatory responses, including colitis." (PMID 37569708, 2023). "The present study proved PHI reduced the production and release of inflammatory factors such as IL-6, IL-1β, and TNF-α in both LPS-induced RAW264.7 cells and DSS-induced colitis mice." (PMID 36768559, 2023). "Compared with WT mice, S1PP2−/− mice had higher intestinal epithelial barrier integrity (manifested as increased expression of E-cadherin) and lower levels of TNF, IL-1β and IL-6 in intestinal tissue in the DSS-induced colitis mouse model." (PMID 37560160, 2023). "DSS-induced mice treated with Sinapic acid had significantly decreased levels of NLRP3, IL-1b, ASC, and Caspase-1, which improved symptoms of colitis.." (PMID 37849728, 2023). "Esculetin has been demonstrated to ameliorate TNBS-induced rat colitis, and attenuate the expression of pro-inflammatory mediators TNF-α and IL-1β." (PMID 37161415, 2023). "The colitis mice with OX treatment exhibited lower levels of AST, ALT, BUN, CR, MDA and a down-regulated expression of IL-6 and IL-1β, while the activity of SOD was up-regulated." (PMID 38060482, 2023). "Increasing evidence has demonstrated that productions of pro-inflammatory cytokines TNF-α, IL-1β and IL-6 are augmented in IBD patients and chemical-induced colitis animal models." (PMID 36830802, 2023). "MC-LR increased the expression of IL-6, IL-1β, TNF-α, and IL-1αin in the DSS-induced colitis model, thereby aggravating the inflammation." (PMID 37505716, 2023).
colitis (continued). "Supplementation with B. vulgatus attenuated symptoms of colitis in mice and decreased the expression of TNF-α, IL-1β, and IL-6 in the colon." (PMID 36902001, 2023). "In mice, TDNPs were found to alleviate colitis symptoms by regulating the expression of pro-inflammatory cytokines (TNF-α, IL-6 and IL-1β) and the antioxidant gene HO-1, while also deactivating the NF-κB pathway." (PMID 37371649, 2023). "The mechanism of expression and inhibition of IL-1β and TNF-α production in intestinal macrophages improved colitis symptoms." (PMID 37371649, 2023). "Combined administration of SM and nano Se can improve anti-inflammatory and antioxidant capacity by reducing the expression of TNF-α, IL-1β, NF-κB, MPO, lipid peroxidation and protein carbonyl, finally relieve symptoms of TNBS-induced colitis." (PMID 37033644, 2023). "TNF, IL1B, and IL6 were increased in Il17b-/- mice compared with WT in colitis in both protein and mRNA levels." (PMID 36814913, 2023). "The expression of Il1a, Ccl5, Il1b, Ccl3, and Cxcl1 were significantly elevated in CD45+ cells from Il17b-/- colitis mice (P < 0.05)." (PMID 36814913, 2023). "Besides, AhR activation by several endogenous ligands, including 6-Formylindolo(3,2-b)carbazole (FICZ), kynurenine and 1,25-dihydroxyvitamin D3 (VD3), could inhibit the NF-κB signaling pathway and reduce IL-1β expression in periodontitis, glioblastoma and colitis." (PMID 36721094, 2023). "In our study, IL-1β, TNF-α, IL-6, and IL-17A contents within the colon increased after CR infection, conforming to prior research regarding CR-induced colitis." (PMID 37111225, 2023). "Loading TNF-α with GELNs can downregulate NLRP3, caspase-1, IL-1β, TNF-α, IL-6 and IL-1b, upregulate anti-inflammatory substances such as IL-10 and IL-22 in colon tissue of DSS-induced colitis mice." (PMID 37033644, 2023). "In line with DSS colitis model results, the secretion of TNF-α, IL-1β, and IL-6, were also obviously reduced in response to LPS when administered with phenolic acids." (PMID 37813835, 2023). "Previous research has revealed that heat-killed L. sakei K040706, which preserve their cell wall components, protect against DSS-induced colitis by suppressing inflammatory mediators such as nitric oxide, TNF-α, IL-1β, and IL-6." (PMID 37317332, 2023). "In a mouse model of colitis induced by dextran sodium sulfate, the NLRP3 inflammasome was activated and shown to be required for production of IL-1β and IL-18, and for dextran sodium sulfate-induced colitis." (PMID 36669831, 2023). "Consistently, IHC staining also confirmed the downregulated expression of IL-1β, IL-6, TNF-α and COX-2 in colitis model of β6-KO mice." (PMID 37223685, 2023). "CsA ameliorated histology damage and the histological scores, decreased inflammatory cytokines (TNF-α and IL-1β) expression and downregulated NE and citH3 expression of NETs-related proteins in DSS-induced colitis mice." (PMID 38093197, 2023). "L. fermentum improved colitis, reduced TNF- α, IL-1β and IL-6 in serum and induced anti-inflammatory cytokine (IL-10) expression in the colons of DSS-induced colitis mice." (PMID 36986118, 2023). "For instance, treatment with geraniol significantly opposed the TNBS-induced colitis effects on the inflammatory parameters, including NFκB, PGE2, IL-1β, ICAM-1, and MPO." (PMID 36009287, 2022). "There is a significant increase in IL-1β and IL-6 mRNA expression in the cortex and IL-1β and TNF-α in the hippocampus of mice with DSS-induced colitis." (PMID 34983592, 2022). "β-myrcene was also effective in preventing the increase in proinflammatory mediators (COX-2 and iNOS) and cytokines (IL-6, IL-1β and TNF-α) at protein and mRNA expression levels and resulting in colitis remission." (PMID 36557879, 2022). "In vivo, DPG decreases the severity of DSS-induced colitis as well as intestinal inflammation reduction mediated by a downregulation of the pro-inflammatory cytokines TNF-α, IL-1β, and IL-6, as well as HMGB1 receptors, RAGE, and TLR4." (PMID 35456938, 2022).